C1QL2 (complement C1q like 2)
Description:
May regulate the number of excitatory synapses that are formed on hippocampus neurons. Has no effect on inhibitory synapses (By similarity).
Synonyms: CTRP10; C1QTNF10
Tractability: Antibody: UniProt places it where antibodies can reach, with medium confidence; UniProt predicts a signal peptide or a membrane-spanning region; its Gene Ontology location is reachable by antibodies, with medium confidence.
Gene: Protein-coding gene on chromosome 2 (119,156,243 to 119,158,751, reverse strand). Ensembl gene ENSG00000144119.
Subcellular location: Secreted
Subcellular location (Human Protein Atlas): Vesicles; Cytosol; Predicted to be secreted
Gene Ontology:
Molecular function: identical protein binding
Biological process: maintenance of synapse structure; trans-synaptic signaling, modulating synaptic transmission; neurotransmitter receptor localization to postsynaptic specialization membrane; postsynaptic density assembly; regulation of synapse maturation
Cellular component: synapse; synaptic cleft; cerebellar climbing fiber to Purkinje cell synapse; extracellular region; glutamatergic synapse; hippocampal mossy fiber to CA3 synapse; protein-containing complex
Genetic constraint (gnomAD): Loss-of-function variants: 13 observed, 14.52 expected, observed/expected ratio (o/e) 0.9, 90% interval 0.58 to 1.42. The synonymous counts are far from expectation, so gnomAD's model fits this gene poorly and the ratio says little. Missense variants: 396 observed, 371.81 expected, observed/expected ratio (o/e) 1.07, 90% interval 0.98 to 1.16. Synonymous variants: 210 observed, 164.5 expected, observed/expected ratio (o/e) 1.28, 90% interval 1.14 to 1.43.
Homologues: Orthologues: chimpanzee C1QL2 (99% identical), macaque C1QL2 (98% identical), dog C1QL2 (95% identical), pig C1QL2 (95% identical), mouse C1ql2 (94% identical), guinea pig C1QL2 (89% identical), rat C1ql2 (84% identical), tropical clawed frog c1ql2 (71% identical), zebrafish c1ql2 (70% identical). Paralogues in human: C1QL3 (65% identical), C1QL1 (60% identical), C1QL4 (56% identical), COL10A1 (32% identical), COL8A2 (31% identical), COL8A1 (30% identical), C1QTNF2 (29% identical), C1QTNF7 (29% identical), C1QTNF9 (29% identical), C1QTNF9B (29% identical), OTOL1 (28% identical), C1QB (27% identical), and 11 more.
Diseases named in the same sentence as C1QL2 in open-access papers:
C1QL2 is named in the same sentence as 14 diseases in open-access papers, as found by Europe PMC text mining. Sharing a sentence is not in itself a finding about the gene and the disease. The quoted sentences say what the papers report.
cocaine addiction (3 papers, 2021 to 2025). "Interestingly, recent studies have also associated C1QL2 with schizophrenia as well as cocaine addiction." (PMID 38358390, 2024). "C1ql2 was also upregulated following IVSA, which is associated with human cocaine addiction using GWAS." (PMID 34155331, 2021).
cocaine use disorder (2 papers, 2025). A substance-related disorder that involves the recurring use of cocaine despite negative consequences. "Genome-wide association studies (GWAS) have implicated CTRP10/C1QL2 in cocaine use disorder." (PMID 37961647, 2025).
schizophrenia (2 papers, 2022 to 2024). A major psychotic disorder characterized by abnormalities in the perception or expression of reality. "The gene C1QL2 (complement C1q like 2) appeared in the greatest proportion of schizophrenia studies, followed by the IEG ARC." (PMID 35941129, 2022).
glioblastoma (1 paper, 2025). The most malignant astrocytic tumor (WHO grade IV). "To investigate the biological relevance of candidate transcription factors enriched in the NSC-like compartment, we next performed functional validation of OTP, C1QL2, and VAX2 using the LN229 glioblastoma cell line (ATCC, CRL-2611)." (PMID 41378293, 2025).
infection (5 papers, 2017 to 2025). The state of being infected such as from the introduction of a foreign agent such as serum, vaccine, antigenic substance or organism. "In addition, the expression of c1ql2, C3, C5, C7, C9, CFB, and complement factor H (CFH) was regulated in rainbow trout stimulated with β-glucan upon infection with A. salmonicida, suggesting improved immune enhancement." (PMID 34835165, 2021).
C1QL2 also shares sentences with these, for which no sentence is quoted: psychiatric disorder (3 papers); dyslipidemia (2); Glucose intolerance (2); Hepatic steatosis (2); Insulin resistance (2); Obesity (2); steatosis (2); breast carcinoma (1); depression (1).